SNORD4A (small nucleolar RNA, C/D box 4A)
Synonyms: Z17A; mgh18S-121; RNU101A
Gene: Small nucleolar RNA gene on chromosome 17 (28,722,582 to 28,722,653, forward strand). Ensembl gene ENSG00000238578.
Gene Ontology:
Biological process: RNA processing
Cellular component: nucleolus
Homologues: Orthologues: chimpanzee SNORD4A (100% identical), macaque SNORD4A (93% identical), pig SNORD4A (86% identical), mouse Snord4a (75% identical), rat Snord4a (75% identical), tropical clawed frog SNORD4A (69% identical). Paralogues in human: SNORD4B (74% identical).